EXT1 (exostosin glycosyltransferase 1)
Diseases named in the same sentence as EXT1 in open-access papers (continued):
Sharing a sentence is not in itself a finding about the gene and the disease.
melanoma (3 papers, 2022 to 2024). A malignant, usually aggressive tumor composed of atypical, neoplastic melanocytes. "EXT1 knockdown was used as model for HSPG deficiency in melanoma cells and associated with increased metastatic spread." (PMID 36982528, 2023). "EXT1 was confirmed to act as a tumor suppressor, shown here for the first time to affect chemosensitivity of melanoma cells." (PMID 36982528, 2023). "Concerning the generalizability of these findings, the relationship of EXT1 and resistance formation is currently derived here from a single melanoma cell line approach." (PMID 36982528, 2023). "Knockdown of EXT1 in MV3 melanoma cells induces resistance against different cytotoxic agents." (PMID 36982528, 2023). "This is the first report on EXT1 activity in sensitizing melanoma cells for treatment." (PMID 36982528, 2023). "In addition, expression of EXT1, but not SLC35B2, was positively correlated with the YAP1/TAZ score in the TCGA cohort of BRAF mutant melanoma, suggesting that EXT1 is a YAP1/TAZ target." (PMID 35798875, 2022). "Aiming to investigate this, we depleted HSPGs by downregulating Exostosin 1 (EXT1), a key enzyme in HS formation, or upregulating heparanase in human MV3 human melanoma cells, and investigated their response to cytotoxic drugs." (PMID 36982528, 2023).
osteosarcoma (3 papers, 2017 to 2025). A usually aggressive malignant bone-forming mesenchymal neoplasm, predominantly affecting adolescents and young adults. "In humans, mutations in either of the exostosin genes EXT1 and EXT2 lead to osteosarcomas or multiple exostoses." (PMID 28068429, 2017). "Mutations in EXT1 or EXT2, members of the EXT family of glycosyltransferases are responsible for hereditary multiple osteochondromas that may degenerate into chondro- or osteo-sarcomas." (PMID 32916872, 2020).
ZIKV infection (3 papers, 2018 to 2025). "Here, we aimed to investigate if the inhibition of ZIKV infection in EXT1 knockout cells was due to the blockage of viral entry caused by HS deficiency on the cell surface." (PMID 39927690, 2025). "This information stimulated us to hypothesize that the deregulation of autophagy caused by EXT1 knockout may be responsible for the restriction of ZIKV infection." (PMID 39927690, 2025). "Altogether, the results from our cell models suggest that knocking out EXT1 wanes the autophagy, which compromises the ZIKV infection." (PMID 39927690, 2025). "The results from ZIKV infection in EXT1-KO and EXT1 over-expression cell model suggest the intricate functions of EXT1 during the ZIKV infection." (PMID 39927690, 2025). "Next, we aimed to examine if EXT1 acts as an essential factor that can boost ZIKV infection when it is over-expressed." (PMID 39927690, 2025). "Collectively, these findings corroborated the conclusion that EXT1 plays dual roles in ZIKV infection at the different stages of infection." (PMID 39927690, 2025). "Here, we showed that EXT1 plays distinct roles in ZIKV infection by remodeling autophagy and regulating viral protein stability." (PMID 39927690, 2025). "To dissect the roles of EXT1 in ZIKV infection, we first used the HEK-293 EXT1 knockout (KO) cells as the cell model." (PMID 39927690, 2025). "In this study, we utilized different EXT1 knockout cell models to study the roles of EXT1 in ZIKV infection." (PMID 39927690, 2025). "Induction of autophagy promotes ZIKV infection, and attenuated autophagy is found in distinct EXT1 knockout (EXT1-KO) cell lines." (PMID 39927690, 2025). "Altogether, our study provides a new understanding of how EXT1 modulates ZIKV infection in different ways and raises interesting questions about EXT1’s roles in virus infection." (PMID 39927690, 2025). "Interestingly, a recent finding highlighted that EXT-1 plays a unique role in the life cycle of Zika virus infection." (PMID 40723871, 2025). "The different roles of EXT1 in ZIKV infection are further confirmed by the data that knocking down EXT1 at the early stage of ZIKV infection represses viral infection, whereas the increase of ZIKV infection is observed when knocking down EXT1 at the late stage of viral infection." (PMID 39927690, 2025). "This study discovers previously unrecognized intricate roles of EXT1 in ZIKV infection." (PMID 39927690, 2025). "In this study, we uncovered the intricate roles of EXT1 during different stages of ZIKV infection." (PMID 39927690, 2025). "Next, we aimed to check if the enhancement of autophagy could restore ZIKV infection in HEK-293 EXT1-KO cells." (PMID 39927690, 2025). "Therefore, we intended to test if EXT1 affects the viral protein stability in ZIKV infection in this set of experiments." (PMID 39927690, 2025). "Altogether, the data indicate that upregulation of EXT1 hampers ZIKV infection." (PMID 39927690, 2025). "All the data suggest that ZIKV does not use HS to assist its cell entry and knockout of EXT1 resulted in the inhibition of ZIKV infection is not because of the deficiency of HS on the cell surface." (PMID 39927690, 2025). "CRISPR/Cas9 screening indicated that NDST1 (N-deacetylase and N-sulfotransferase 1) and EXT1 might function as cell-dependent factors of ZIKV infection." (PMID 39927690, 2025). "To rule out the possible off-target effects from CRISPR-Cas9 on ZIKV infection, we employed mouse embryonic fibroblast (MEF) EXT1-KO cells as another cell model to confirm the finding." (PMID 39927690, 2025). "To rule out the possible effects of plasmid transient transfection on ZIKV infection, we constructed the HEK-293 cells stably expressing EXT1 (HEK-293-EXT1) and used it as a model to assess the impacts of EXT1 on ZIKV infection." (PMID 39927690, 2025).
ZIKV infection (continued). "We found that ZIKV cell entry is not dependent on HS and the expression of EXT1 modulates ZIKV infection by regulating autophagy and viral envelope protein stability via a proteasome degradation way." (PMID 39927690, 2025). "Knocking out EXT1 dramatically restricts ZIKV infection, which is not due to the inhibition of virus entry resulting from HS deficiency, but mediated by the downregulation of autophagy." (PMID 39927690, 2025).
atherosclerosis (2 papers, 2017 to 2024). A disease characterized by the build-up of fatty material and calcium deposition in the arterial wall resulting in partial or complete occlusion of the arterial lumen. "However, EXT1 expression is not significantly regulated in M2-like macrophages from patients with chronic lung diseases, suggesting a different role for EXT1 under these conditions compared to other diseases like rheumatoid arthritis and atherosclerosis, where EXT1 expression is increased." (PMID 38886662, 2024).
autism spectrum disorder (2 papers, 2019). A spectrum of developmental disorders that includes autism, and Asperger syndrome. "Furthermore, a SNP in EXT1 was the most significant genic association (2.94 × 10-7) in a recent GWAS from the ASD working group of the PGC (Autism Spectrum Disorders Working Group of the Psychiatric Genomics Consortium, 2017)." (PMID 31316544, 2019).
breast tumor (2 papers, 2018 to 2024). "C2 and C5 mainly resided in breast tumors and expressed tumor suppressor genes (EXT1 and HPSE2), which may regulate the heparan sulfate in the breast TME; C13 mainly resided in breast NAT and highly expressed LRP1B, a putative tumor suppressor that may inhibit cancer migration and invasion." (PMID 38010945, 2024).
cervical cancer (2 papers, 2022). A primary or metastatic malignant neoplasm involving the cervix. "In addition to stimulate HCC cell growth, higher expression of EXT1 was associated with poor prognosis in lung, thyroid, and cervical cancers in TCGA." (PMID 35710421, 2022). "Compared with normal cervix tissues, the expressions of several glycosyltransferases in cervical cancer tissues were upregulated, including GALNT2, POGLUT1, EXT1, B3GAT3, B4GALNT1 and UGT8 (GSE9750)." (PMID 36110252, 2022).
colon cancer (2 papers, 2021 to 2023). "To examine EXT1 expression in fibroblasts in the stroma of human colon and pancreatic cancers, we collected surgical specimens and performed immunostaining for EXT1 in both cohorts (colon cancer, n = 42; pancreatic cancer, n = 48)." (PMID 36809261, 2023). "A correlation between EXT1 and αSMA expression was observed more in colon cancer than in pancreatic cancer." (PMID 36809261, 2023).
colorectal cancer (2 papers, 2021). A primary or metastatic malignant neoplasm that affects the colon or rectum. "However, suggestive significance was found between PIK3CB and colorectal cancer on the left side (p = 0.0007), androgen receptor (AR) and female gender (p = 0.0002), TGM7 and young patient (p = 0.002), and EXT1 and late stage." (PMID 34207827, 2021).
glomerulosclerosis (2 papers, 2021 to 2022). A hardening of the kidney glomerulus caused by scarring of the blood vessels. "In patients with EXT1/EXT2-positive antigens compared to patients with EXT1/EXT2-negative antigens; nephrotic proteinuria is found more often in patients with membranous lupus nephritis, than in patients with decreasing glomerulosclerosis and renal fibrosis." (PMID 36176440, 2022). "In membranous lupus nephritis EXT1/EXT2-positive patients have compared to EXT1/EXT2-negative patients more often nephrotic proteinuria, but less glomerulosclerosis and interstitial fibrosis." (PMID 33828546, 2021).
lung adenocarcinoma (2 papers, 2019 to 2022). A carcinoma that arises from the lung and is characterized by the presence of malignant glandular epithelial cells. "With the increasing risk score of patients with lymph node metastasis of lung adenocarcinoma, the expression of high-risk mRNAs (HMMR, B4GALT1, ANGPTL4, EXT1, GPC1, RBCK1, SOD1, AGRN) was obviously upregulated." (PMID 31847905, 2019).
lymphoma (2 papers, 2021 to 2023). A malignant (clonal) proliferation of B- lymphocytes or T- lymphocytes which involves the lymph nodes, bone marrow and/or extranodal sites. "Given the broad range of effects of EXT1 through heparan sulphate biosynthesis and its role as a tumour suppressor, it is possible this gene could be involved in lymphoma, but this has yet to be reported." (PMID 37756103, 2023).
metastatic tumor (2 papers, 2012 to 2015). "The only exception being EXT1, which appeared downregulated on average about 4 fold (p = 0.01) in 90 % of patients with non-metastatic tumors." (PMID 26482785, 2015). "In our data, the most remarkable change in metastatic tumor was occurred at increases (≧1.30) of D1S1635 (1p36.22), D1S214 (1p36.31), EXT1 (8q24.11-q24), AFM137XA11 (9p11.2), CCND2 (12p13), 8 M16/SP6 (12ptel), IGH (D14S308), HIC1 (17p13.3), 282 M15/SP16 (17ptel), and LAMA3 (18q11.2)." (PMID 23199169, 2012).
Osteopenia (2 papers, 2008 to 2026). Osteopenia is a term to define bone density that is not normal but also not as low as osteoporosis. "Furthermore, osteopenia has been shown to be associated with HME in a family that carries a mutation in EXT1." (PMID 18654627, 2008).
periodontitis (2 papers, 2019 to 2024). An acute or chronic inflammatory process that affects the tissues that surround and support the teeth. "The initial comparison of group means for total expression domains of all investigated factors at level of significance α = 0,01 revealed that only EXT1 is differentially regulated in periodontitis (p = 4,5519 × 10–6)." (PMID 31611818, 2019). "Interestingly, HPSE1, EXTs, and NDSTs displayed similar correlation pattern in control and periodontitis group – positive correlations were found for EXT1, EXT2 and NDST1." (PMID 31611818, 2019). "The heparan sulphate biosynthesis enzymes (EXT1, EXT2, NDST1, and NDST2) displayed comparable correlation with the gingival tissue inflammatory infiltrate in the periodontitis group (EXT1, EXT2 and NDST1 correlated positively, and NDST correlated negatively)." (PMID 38674142, 2024). "Of all investigated factors, the expression domains of Sdc1, HPSE1, EXT1, and NDST1 in gingival tissue displayed statistically significant differences between control and periodontitis group." (PMID 31611818, 2019). "However, the stromal expression domains of Sdc1 (p = 1,1033 × 10–6), HPSE1 (p = 0,0023), EXT1 (p = 1,2849 × 10–7), NDST1 (p = 0,000105), and CD45 (p = 0,003747) showed significant difference between controls and periodontitis group." (PMID 31611818, 2019). "However, the differential expression profiles of EXT1, NDST1 and HPSE1 do imply that certain perturbations in stromal HS content and composition might occur in periodontitis and might be responsible for dysregulation of inflammatory response." (PMID 31611818, 2019).
rheumatoid arthritis (2 papers, 2018 to 2024). A chronic, systemic autoimmune disorder characterized by inflammation in the synovial membranes and articular surfaces. "IPA of annotated transcripts showed similar activation of osteogenic-associated pathways such as roles of osteoblasts, osteoclasts, and chondrocytes in rheumatoid arthritis as well as the expression of typical osteogenic genes such as dlx5, tsc22d3, alpl, klf4, ext1, and stc1 in both datasets." (PMID 30376879, 2018).
viral infection (2 papers, 2025). "Knocking down EXT1 at the early stage represses viral infection, whereas it increases virus infection when knockdown is performed at the late stage of viral infection." (PMID 40723871, 2025). "In addition to the function as the regulator of HS to affect virus infection, EXT1 was reported to impede viral production by promoting viral protein degradation." (PMID 39927690, 2025). "However, our current study only scratches the surface of EXT1’s multifaceted roles in virus infection." (PMID 39927690, 2025).
achondroplasia (1 paper, 2012). Achondroplasia is the most common form of chondrodysplasia, characterized by rhizomelia, exaggerated lumbar lordosis, brachydactyly, and macrocephaly with frontal bossing and midface hypoplasia. "The EXT1 and EXT2 genes (30 cases) for multiple cartilaginous exostoses, the FBN1 gene for Marfan syndrome (24 cases), and the FGFR3 gene for achondroplasia (22 cases) were most frequently reported in Chinese biomedical literature from the CBM database." (PMID 22913777, 2012).
Arrhythmia (1 paper, 2023). Any cardiac rhythm other than the normal sinus rhythm. "PTPRQ, PLEKHB2, IL1RAPL1, and EXT1 are predicted to be involved in biological processes such as heart and large blood vessel development, as well as cardiac phenotypes such as arrhythmias, valve diseases, and cardiomyopathy." (PMID 37684230, 2023).
Ataxia (1 paper, 2020). Ataxia refers to impaired coordination of voluntary muscle movement. "However, in the postnatal stage, EXT1 is expressed in the cerebellum, which may correlate with the symptoms seen in MS such as ataxia." (PMID 32398079, 2020).
bladder cancer (1 paper, 2022). "For instance, low expressions of glycosyltransferase genes B4GALT1, EXT1, MGAT5B and POFUT1 predicted poor patient’s survival in bladder cancer." (PMID 36110252, 2022).
Burkitt lymphoma (1 paper, 2021). A rare form of malignant mature B-cell non-Hodgkin lymphoma. "Interestingly, these cells lack HS on the cell surface, but exogenous expression of the HS elongation factors EXT1 or EXT2 can restore HS expression in several Burkitt lymphoma cell lines." (PMID 34648606, 2021).
emphysema (1 paper, 2022). "Palovarotene, a retinoic acid receptor and selective agonist for EXT1/EXT2-CDG, has already shown clinical safety for fibrodysplasia ossificans progressiva and emphysema." (PMID 35955863, 2022).
familial nephropathy (1 paper, 2018). "Mutations in EXT1 that encodes exostosin-1 is a cause for AD familial nephropathy and multiple exostoses has been associated with SSNS in an adult patient, but the reported patient also received cyclosporine A and cyclophosphamide in addition to steroids to induce full remission." (PMID 29594119, 2018).
femoral neck fracture (1 paper, 2024). Fractures of the short, constricted portion of the thigh bone between the femur head and the trochanters. "The immunohistochemical expressions of SDC1, SDC2, SDC4, EXT1, EXT2, NDST1 and NDST2 in synovial intima and subintima were then analysed and compared with the control group (patients with femoral neck fracture)." (PMID 38674142, 2024).
glomerular disease (1 paper, 2025). "However, this survey identified that nephrologists have limited access to testing and exposure to antigens other than PLA2R, THSD7A, NELL1, and EXT1/2 even amongst glomerular disease experts." (PMID 40500560, 2025).
heart failure (1 paper, 2022). Inability of the heart to pump blood at an adequate rate to meet tissue metabolic requirements. "We found that significant upregulation of EXT1 and EXT2 was closely associated with cardiac fibrosis and heart failure in DCM, which partly explained the potential molecular mechanism of HS biosynthetic activation in DCM." (PMID 35711374, 2022).
Insulin resistance (1 paper, 2025). Increased resistance towards insulin, that is, diminished effectiveness of insulin in reducing blood glucose levels. "Our results show that reduced HS sulfation and impaired HS production via Ndst1 and Ext1 inactivation in AT, respectively, promote glucose intolerance and insulin resistance by attenuating the endogenous FGF1-metabolic activity." (PMID 41072794, 2025).
malignant glioma (1 paper, 2026). A grade III or grade IV glioma arising from the central nervous system. "In contrast to EXT1, EXT2 was predominantly expressed in malignant glioma cell populations, particularly those enriched in mesenchymal and contractile gene signatures." (PMID 41438585, 2026). "These IHC results thus provide wet-lab validation of our computational model, confirming that EXT1 activation is not merely transcriptional but extends to the protein level within malignant glioma compartments." (PMID 41438585, 2026).
meningioma (1 paper, 2018). A generally slow growing tumor attached to the dura mater. "RUNDC3B, SCG2, SLC1A3, EXT1 (as well as RHOBTB3, TSPAN7, CAV2, MLPH) were part of the NF2/SMARCB1 expression subclass of a recent study on genomic profiling of meningioma." (PMID 29662628, 2018).
multiple endocrine neoplasia type 1 (1 paper, 2025). An autosomal dominant tumor predisposition syndrome caused by pathogenic variants in the MEN1 gene, characterized by an increased risk of tumors of the parathyroid glands, pituitary gland, and foregut neuroendocrine tumors (most commonly pancreatic islet cells). "Finally, in 2015, a German group reported a case of multiple endocrine neoplasia type 1 (MEN1) in a 47-year-old man carrying both a novel EXT1 mutation and a pathogenic variant in the MEN1 gene." (PMID 41441317, 2025).
oligodendroglioma (1 paper, 2026). A well-differentiated (WHO grade II), diffusely infiltrating neuroglial tumor, typically located in the cerebral hemispheres. "EXT1 and EXT2 were particularly enriched in recurrent GBM and oligodendrogliomas, consistent with EXT1's vascular-stromal localization and EXT2's mesenchymal distribution." (PMID 41438585, 2026).
osteopoikilosis (1 paper, 2010). A rare autosomal dominant inherited disorder characterized by the presence of small areas of increased density throughout the bones. "Surprisingly, three of the osteopoikilosis affected patients additionally to LEMD3 mutation carried a yet unreported amino acid variant (p.A578T) in the EXT1 gene." (PMID 20618940, 2010). "The patients affected with both LEMD3 and EXT1 gene mutations displayed typical features of the osteopoikilosis." (PMID 20618940, 2010). "Another new substitution G > A was found in EXT1 gene at position 1732 (cDNA) in Exon 9 (p.A578T) in three out of five osteopoikilosis affected family members." (PMID 20618940, 2010). "We investigated LEMD3 and EXT1 in the three-generation family from Poland, with 5 patients affected with osteopoikilosis and one child affected with multiple exostoses." (PMID 20618940, 2010).